FZD5 (frizzled class receptor 5)
Diseases named in the same sentence as FZD5 in open-access papers (continued):
Sharing a sentence is not in itself a finding about the gene and the disease.
coloboma (5 papers, 2015 to 2025). An abnormality in which a part of a structure in one or both eyes is missing. "Collectively, our results suggest that zebrafish embryos can compensate for loss of Fzd5 activity, but fzd5 mutants are predisposed to developing microphthalmia and coloboma in conditions in which Wnt activity is further compromised." (PMID 40401611, 2025). "Variants of FZD5 in humans have been shown to lead predominantly to isolated coloboma and less frequently to coloboma and microphthalmia; but, to date, there is no clear understanding of the cause of this phenotypic variability." (PMID 40401611, 2025). "Recent studies have uncovered a series of variants of FZD5 associated with microphthalmia and/or coloboma in humans." (PMID 40401611, 2025). "Conditional loss of function of Fzd5 in the mouse eye leads to microphthalmia, coloboma and persistent foetal vasculature, phenotypes that are exacerbated when the function of Fzd8, co-expressed with Fzd5 in the eye primordium, is downregulated." (PMID 40401611, 2025). "Heterozygosity for frameshift, nonsense and missense variants across various domains of FZD5 have been involved in isolated or complex ocular coloboma." (PMID 39503780, 2024). "Mutations in the Wnt receptor FZD5, which is expressed throughout eye development, have been linked to both isolated and complex forms of coloboma." (PMID 39503780, 2024). "A conditional fzd5 loss-of-function model in the eye has been reported to result in microphthalmia, coloboma, and persistent foetal vasculature." (PMID 39503780, 2024). "Here, we present a case of syndromic bilateral ocular coloboma with microcornea, bone developmental anomalies, and mild intellectual disability whose exome sequencing analysis identified homozygosity for an ultra-rare FZD5 missense variant (p.Pro267Leu)." (PMID 39503780, 2024). "Additionally, the results presented here suggest that biallelic variants in FZD5 could be responsible for syndromic forms of ocular colobomas." (PMID 39503780, 2024). "Similar non-penetrance has been observed in families with pathogenic variants of FZD5, a gene in the WNT pathway that causes coloboma." (PMID 32571845, 2020). "A proportion of the FZD5 cases described in humans have been shown to carry variants also in other loci, and, at least in one case, compound variants of FZD5 and another gene (DDX3X) required for eye morphogenesis and leading by itself to coloboma has been described." (PMID 40401611, 2025). "Furthermore, both germline and conditional deletion of the Wnt ligand receptor Fzd5 can result in abnormal eye development, including failure of the ventral fissure to close (coloboma)." (PMID 25715397, 2015).
microphthalmia (5 papers, 2013 to 2025). Congenital or developmental anomaly in which the eyeballs are abnormally small. "Except for BMP4, opposite ocular phenotypes have been associated with mutations in other genes, such as FZD5, in which individuals with the same truncation variant or different eyes of the same individual exhibited either microphthalmia/uveal coloboma or high myopia." (PMID 34926457, 2021). "Frizzled class receptor 5 (FZD5) is a Wnt receptor expressed in the developing eye, and individuals with variants in FZD5 exhibit microphthalmia/coloboma, supporting a role for this receptor in human eye formation." (PMID 40401611, 2025). "Mutations in the same gene resulting in both high myopia and microphthalmia have been observed for a few other genes like FZD5 and PAX6, suggesting bidirectional roles of these genes in early ocular development." (PMID 34926457, 2021).
pancreatic ductal adenocarcinoma (5 papers, 2018 to 2025). An infiltrating adenocarcinoma that arises from the epithelial cells of the pancreas. "Knockout of FZD5 robustly inhibited cell growth in human Ring finger protein 43 (RNF43)-mutant pancreatic ductal adenocarcinoma cells (PDAC) in clonogenic growth assays, and editing of FZD5 significantly inhibited the expression of WNT target genes AXIN2 and NKD1(Naked cuticle homolog 1)." (PMID 29789460, 2018). "In Wnt‐addicted pancreatic ductal adenocarcinoma (PDAC), cholesterol stimulates tumor growth via Fzd5‐mediated Wnt/β‐catenin signaling." (PMID 35975457, 2022).
glioma (4 papers, 2020 to 2022). A benign or malignant brain and spinal cord tumor that arises from glial cells (astrocytes, oligodendrocytes, ependymal cells). "Peng at al reported that in addition to being upregulated in high-grade gliomas, CTHRC1 expression correlated with genes associated with the Wnt Signaling pathway (DVL3, DVL1, DVL2, ROR2, WNT3A, FZD6 and FZD5)." (PMID 36190948, 2022).
acute myeloid leukemia (3 papers, 2021 to 2023). Acute myeloid leukemia (AML) is a group of neoplasms arising from precursor cells committed to the myeloid cell-line differentiation. "FZD5 and FZD8 have roles in early development in both pancreatic cancer and acute myeloid leukemia." (PMID 34604862, 2021). "Specifically in acute myeloid leukemia (AML), WNT10B signals through FZD4 and FZD5, while in T-cell acute lymphoblastic leukemia, WNT10B signals through FZD6." (PMID 36814601, 2023).
diabetes (3 papers, 2020 to 2025). "this study identified clinically relevant non-coding RNA–based angiogenesis panel (FZD5, GTF2I mRNAs, hsa-miR-1976 and LINC02210 lncRNA) as a biomarker signature associated with type 2 diabetes mellitus complicated by ischemic heart disease." (PMID 41244042, 2025). "The mechanisms leading to ISCs quiescence play an important role in regulating islet function via the Wnt5a-Fzd5 system and can help us understand the crosstalk between cells inside the islets of Langerhans and serve as a target for the prevention of diabetes." (PMID 32184820, 2020). "Our objective was to determine the discriminatory performance of a molecular RNA panel comprising FZD5 and GTF2I for the early identification of ischemic heart disease in individuals with type 2 diabetes mellitus." (PMID 41244042, 2025). "In our data, FZD5, GTF2I, hsa-miR-1976, and LINC02210 effectively differentiated T2DM from T2DM+IHD, consistent with prior reports identifying ncRNA signatures as candidate predictors of IHD in diabetes." (PMID 41244042, 2025). "Therefore, we evaluated whether a molecular RNA panel comprising FZD5 and GTF2I could facilitate the early detection and discrimination of ischemic heart disease in individuals with type 2 diabetes mellitus." (PMID 41244042, 2025).
gastric cancer (3 papers, 2021 to 2024). A primary or metastatic malignant neoplasm involving the stomach. "Pathway enrichment analysis of FZD5 using TCGA database showed that FZD5 is negatively associated with EMT in 375 gastric cancer tissues and 32 normal gastric tissues." (PMID 33618713, 2021). "Unexpectedly our study uncovered that FZD5 prevents EMT and is associated with longer survival in gastric cancer, suggesting FZD5 as a putative suppressor in this type of cancer." (PMID 33618713, 2021). "Intriguingly, Yap/Taz is modulated by WNT5A, suggesting that FZD5 signaling may be suppressed by WNT5A in gastric cancer." (PMID 33618713, 2021). "In contrast to other FZDs, FZD5 was identified to prevent EMT in gastric cancer." (PMID 33618713, 2021). "However, our study revealed that FZD5 is a putative suppressor in gastric cancer." (PMID 33618713, 2021). "Furthermore, our study showed that WNT7B is a putative ligand for FZD5 in gastric cancer." (PMID 33618713, 2021). "FZD5 maintains the epithelioid phenotype of gastric cancer cells, inhibits EMT of gastric cancer, and reduce its metastatic potential." (PMID 38952556, 2024). "FZD5, ELF3, TEAD1 and SNAI2 expression in 55 gastric cancer tissues was detected by immunohistochemistry." (PMID 33618713, 2021). "However, our study warns out that targeting FZD5 should be cautious and tumor-specific, since treatment with these antibodies may potentially promote metastasis in some other types of cancers including gastric cancer." (PMID 33618713, 2021). "In contrast to other isoforms, FZD5 and FZD6 play anti-oncogenic roles in gastric cancer." (PMID 38952556, 2024). "Interrogation of CCLE database revealed that FZD5 is positively correlated with epithelial-related factors CDH1 (E-cadherin), OCLN (Occludin), EPCAM and ELF3, while negatively correlated with mesenchymal-related factors VIM (Vimentin), SNAI2 (Slug), ZEB1 and ZEB2 in 37 gastric cancer cell lines." (PMID 33618713, 2021).
asthma (2 papers, 2023 to 2025). "Expression of WNT3, WNT5a, WNT10, and their receptor, Fzd-5, positively correlated with type 2-high asthma in adults whereas expression of WNT5b negatively correlated with type 2 inflammation." (PMID 37814791, 2023). "Given the expression of FZD5 and TCF7L2 in the endodermal foregut lineage cell types, we also performed SMR focusing on foregut-related tissue and phenotypes, which showed some enrichment for respiratory phenotypes including asthma." (PMID 39904980, 2025).
endometrial adenocarcinoma (2 papers, 2011 to 2018). "Here, we showed that FZD5 is downregulated in type I endometrial adenocarcinoma, compared with atrophic endometrium." (PMID 22069131, 2011). "FZD5 is downregulated in endometrial adenocarcinoma, in comparison with atrophic endometrium." (PMID 22069131, 2011).
liver cancer (2 papers, 2021 to 2024). An epithelial or non-epithelial malignant neoplasm that arises from the liver. "However, it promoted liver tumorigenesis in HCC mice models via initiation of liver cancer stem cells (LCSCs) through Wnt5b‐Fzd5 mediating β‐catenin signaling." (PMID 33931972, 2021). "The translation of FZD5 mRNA was promoted by YTHDF1 in an m6A-dependent manner, which subsequently facilitated liver cancer progression." (PMID 39735608, 2024).
lung carcinoma (2 papers, 2021 to 2022). "Moreover, interrogation of CCLE database showed that FZD5 is also associated with epithelial-like phenotype in lung cancer (data not shown)." (PMID 33618713, 2021).
myopia (2 papers, 2014 to 2021). "The amounts of Wnt2b, Fzd5 and β-catenin mRNA and protein were significantly greater in form-deprived myopia eyes than in control eyes.DKK-1 (antagonist) reduced the myopic shift in refractive error and increase in axial elongation, whereas Norrin had the opposite effect in FDM eyes." (PMID 24755605, 2014).
osteoarthritis (2 papers, 2021 to 2025). A noninflammatory degenerative joint disease occurring chiefly in older persons, characterized by degeneration of the articular cartilage, hypertrophy of bone at the margins and changes in the synovial membrane. "Furthermore, Fzd5 levels are higher in RA synovium in comparison to osteoarthritis and normal adult synovium." (PMID 34211463, 2021).
pancreatic adenocarcinoma (2 papers, 2018 to 2020). "Signaling via Fzd5 in these tumor cells was shown to be crucial in β-catenin-mediated proliferation and treatment of these pancreatic adenocarcinoma cells with Fzd5 antibodies led to inhibited cell growth, both in vitro and in xenograft models in vivo." (PMID 29845518, 2018). "For example, genome-scale pooled CRISPR screening technology was applied to identify vulnerabilities in RNF43(ring finger protein-43)-mutant pancreatic adenocarcinomas, finding FZD5 (frizzled class receptor 5) as a common vulnerability that can be exploited therapeutically." (PMID 31947935, 2020). "Our data demonstrate the importance of Fzd5 in ECs during angiogenesis and might imply that targeting the Fzd5 in these types of tumors not only affects the pancreatic adenocarcinoma cells, but could in addition potentially result in beneficial suppression of tumor vascularization." (PMID 29845518, 2018).
preeclampsia (2 papers, 2013 to 2025). Preeclampsia is a hypertensive disorder of pregnancy that is characterized by new-onset hypertension with proteinuria presenting after 20 weeks of gestation, and depending on mild or severe forms may initially present with severe headache, visual disturbances, and hyperreflexia. "RT‒qPCR analysis confirmed the upregulation of FKBP5, LAMA5, FZD5 and FGG mRNA expression in preeclampsia." (PMID 40490753, 2025).
psoriasis (2 papers, 2009 to 2012). An autoimmune condition characterized by red, well-delineated plaques with silvery scales that are usually on the extensor surfaces and scalp. "We included Fzd3 and Fzd5 in this analysis, since these have been reported to bind Wnt5a, as well as Fzd6, as it was found upregulated in psoriasis and squamous cell carcinoma." (PMID 19399181, 2009). "In line, Wnt5a and fzd5 are both overexpressed and re-distributed in the epidermis of psoriasis which involves disturbed keratinocyte differentiation." (PMID 19399181, 2009). "We next characterized the expression of Wnt5a, Fzd3, Fzd5, Fzd6 in psoriasis lesions which are characterized by hyperproliferation and dysregulated differentiation." (PMID 19399181, 2009). "Taken together, Wnt5a, Fzd5, and Fzd6 are strongly upregulated in psoriasis." (PMID 19399181, 2009). "The marked overexpression of Wnt5a and Fzd5 in psoriasis suggest that this ligand-receptor pair may actively drive the chronic inflammatory and hyperproliferative nature of this phenotype." (PMID 19399181, 2009). "In addition, we previously found Fzd5 also upregulated in psoriasis." (PMID 22384081, 2012). "Fifth, our data show that dermal fibroblasts in psoriasis are strongly positive for Wnt5a and activated fibroblasts from rheumatoid arthritis are synthesize inflammatory cytokines, most notably IL15, subsequent to Wnt5a/Fzd5 signalling." (PMID 19399181, 2009).
renal cell carcinoma (2 papers, 2024 to 2025). "Renal cell carcinoma (RCC) tissues have been demonstrated to have considerably increased levels of FZD5 and FZD8 mRNA." (PMID 40171220, 2025).
rheumatoid arthritis (2 papers, 2009 to 2016). A chronic, systemic autoimmune disorder characterized by inflammation in the synovial membranes and articular surfaces. "In synoviocytes from rheumatoid arthritis patients, the expressions of Wnt5a and Frizzled5 (Fzd5) were significantly enhanced and their blockades inhibited synoviocyte activation." (PMID 26789270, 2016).
acute coronary syndrome (1 paper, 2025). Signs and symptoms related to acute ischemia of the myocardium secondary to coronary artery disease. "has-miR-1976 was found to interact with the selected genes, FZD5 and GTF2I and was strongly linked to acute coronary syndrome and diabetic nephropathy progression." (PMID 41244042, 2025).
atherosclerosis (1 paper, 2023). A disease characterized by the build-up of fatty material and calcium deposition in the arterial wall resulting in partial or complete occlusion of the arterial lumen. "ROR2 was included as a co-receptor of FZD5 because it was proposed as a proinflammatory receptor for Wnt5a in atherosclerosis and lung COPD." (PMID 35622188, 2023).
basal cell carcinoma (1 paper, 2022). A carcinoma involving the basal cells. "Among the DEGs in PA, we identified enrichment in cancer pathways (e.g., basal cell carcinoma) among the most relevant KEGG pathways, and significant downregulation of growth-related genes such as Wnt6 (Wnt Family Member 6, FC = −2.019, p = 4.18E-05) and FZD5 (frizzled-5, FC = −1.493, p = 0.0001)." (PMID 36046021, 2022).
bladder cancers (1 paper, 2024). "Our group previously found that FZD5 is implicated in the maintenance of an epithelial phenotype in gastric and bladder cancers." (PMID 38539211, 2024).
bone sarcoma (1 paper, 2015). A sarcoma that arises from the bone. "We found that FZD3, FZD5, FZD9 and FZD10 were prominently expressed in all bone sarcoma cells as compared to hMSC." (PMID 25999350, 2015).
capillary hemangioma (1 paper, 2024). A common hemangioma characterized by the presence of capillary-sized vascular channels without prominent epithelioid endothelial cells. "This has been attributed to the unexpected binding to vascular endothelial growth factor receptor 2, frizzled class receptor 5, and UL16 binding protein 2 that may correlate with the side effects of capillary hemangiomas observed in clinical studies with camrelizumab." (PMID 38176728, 2024).
clear cell carcinoma (1 paper, 2012). "Kidney tumor tissue arrays showed Fzd5 membrane staining in 30% of clear cell carcinoma, with nuclear cyclin D1 showing a strong correlation with the Fzd5 membrane labeling." (PMID 22325146, 2012).
colitis (1 paper, 2015). Inflammation of the colon. "Non-canonical WNT pathway elements represented by FZD5, WNT5A and NFATc1 were remarkably elevated in colitis IELs." (PMID 26652024, 2015).
colorectal tumor (1 paper, 2025). "Our results provide an underlying mechanism for a recent study in which the authors reported that FZD5, but not the other FZDs, is crucial for the growth of RNF43-mutated pancreatic tumors and colorectal tumor organoids." (PMID 39463927, 2025).
deep venous thrombosis (1 paper, 2025). "We found significant associations between eQTL-mediated changes in TMEM88, NDRG2 and FZD5 expression with myocardial and vascular traits including heart rate and deep venous thrombosis." (PMID 39904980, 2025).
diffuse large B-cell lymphoma (1 paper, 2021). "Downregulation of FZD5 was observed in CD30+ diffuse large B-cell lymphoma (DLBCL)." (PMID 33618667, 2021).
endotoxemia (1 paper, 2015). "In the present study, we measured the key components of Wnt5a signaling pathway in the lung of endotoxemia rats to gain further insights into Wnt5a/Fzd5/CaMKII biology." (PMID 26218875, 2015).
exudative vitreoretinopathy (1 paper, 2024). Familial exudative vitreoretinopathy (FEVR) is a rare hereditary vitreoretinal disorder characterized by abnormal or incomplete vascularization of the peripheral retina leading to variable clinical manifestations ranging from no effects to minor anomalies, or even retinal detachment with blindness. "The identification of a heterozygous, dominant FZD4 variant (p.Pro251Arg) in a patient with familial exudative vitreoretinopathy (FEVR) raises questions about how the FZD5 p.Pro267Leu variant, affecting the same conserved amino acid, leads to a recessive phenotype." (PMID 39503780, 2024).
fibrosis (1 paper, 2021). the formation of excess fibrous connective tissue in an organ or tissue in a reparative or reactive process. "In conclusion, pressure overload enhances the secretion of Wnt5a or Wnt11 from CMs and CFs which promotes cardiac fibrosis by activation the crosstalk of FZD5 and EGFR." (PMID 34564708, 2021).
gastric tumors (1 paper, 2020). "Given that gut-specific knockout of FZD5 is feasible in the mouse models, it is likely that targeting of FZD5 can be used in RNF43 mutated intestinal or gastric tumors." (PMID 33291655, 2020).
kidney cancer (1 paper, 2020). Primary or metastatic malignant neoplasm involving the kidney. "Subsequent Western blot analysis confirmed the increase in Fzd5 content in kidney cancer compared to a healthy kidney." (PMID 33330038, 2020). "The aim of this study is immunohistochemical evaluation and comparison of the expression of the WNT10A, Fzd5, β-catenin, GSK-3ß, CacyBP/SIP, and LMP7 genes in human kidney cancer tissue in different histological types of RCC." (PMID 33330038, 2020).
leukemia (1 paper, 2023). A malignant (clonal) hematologic disorder, involving hematopoietic stem cells and characterized by the presence of primitive or atypical myeloid or lymphoid cells in the bone marrow and the blood. "The resistant leukemia cell lines showed increased transcription levels of WNT/β‐catenin target genes DVL1, GSK3B, and FZD5." (PMID 36567628, 2023).
myeloma (1 paper, 2021). "MM-MSCs and pre-OBs from myeloma patients exhibited decreased levels of Ror2, and co-culture with myeloma cells downregulated the expression of both FZD5 and Ror2, thus contributing to reduced OB differentiation." (PMID 34067236, 2021).
nasal polyp (1 paper, 2012). "Notably, we found that the genes involved in the Wnt pathway were enriched (P = 0.026), and four genes (FZD5, LRP6, PPP2R1B, and TBL1XR1) in this pathway switched to proximal APA sites in nasal polyp tissue." (PMID 23185289, 2012).